FANCA (FA complementation group A)
Diseases named in the same sentence as FANCA in open-access papers (continued):
Sharing a sentence is not in itself a finding about the gene and the disease.
Fanconi anemia (continued). "Indeed, the decrease in proliferation observed in TMEM45A-inactivated cells may be explained by the deregulation of the expression of genes implicated in G2/M transition pathway such as FANCA (Fanconi Anemia Complementation Group A) and ARPP19 (CAMP Regulated Phosphoprotein 19)." (PMID 31801939, 2019). "At 16q24, imputed expression levels of two genes were negatively associated with cSCC: CDK10 (cyclin dependent kinase 10) imputed in all four tested tissue types, and FANCA (Fanconi anemia complementation group A) imputed in LCLs." (PMID 30323283, 2018). "WES revealed that HMCLs displayed frequent mutations in Fanconi anemia genes (PALB2 [12%], FANCI [12%], FANCA [9%], FANCD2 [9%], BRCA2 [9%]) as well as in helicases (such as RECQL4, 15%, and BLM, 15%) and epigenetic modifiers (e.g., TET2, 15% and SETD2, 6%)." (PMID 30545397, 2018). "Six patients had mutations in FANCA, FANCI, FANCL, FANCM and SLX4 genes, which are involved in Fanconi anemia (FA)." (PMID 28423363, 2017). "Specifically, we identified as interactors, or in our phosphoproteome analysis, repair proteins such as MSH6 (DNA mismatch repair protein Msh6) and FANCA (Fanconi Anemia, complementation group A)." (PMID 28710492, 2017). "FANCA has been found to exist in a large nuclear protein complex that contains the Fanconi anemia core complex and the Bloom syndrome BLM complex." (PMID 24349332, 2013). "Deficiency of each gene shows similar clinical and cellular phenotypes; however, approximately 66% of Fanconi anemia patients presents with defective FANCA." (PMID 24349332, 2013). "For example, Cluster 1 includes four members of the Fanconi anemia complementation group (FANCA, D2, E and G)." (PMID 18922151, 2008). "FANCA and five other Fanconi anaemia genes code for components of a complex that is required for the ubiquitination of FANCD2 in response to DNA damage." (PMID 15860134, 2005). "FANCA variations are the most frequent in Fanconi anemia and, according to recent reports, it might be the only FANC gene involved in hereditary cancer." (PMID 37182128, 2023). "FANCA is essential for the function of Fanconi anemia (FA) pathway." (PMID 35800363, 2022). "Additionally, mutations in the Fanconi Anemia genes, FANCM (1, 1.8%) and FANCA (1, 1.8%), were also found." (PMID 35205662, 2022). "In the human condition Fanconi Anaemia, metabolic ROS were shown to induce DNA damage in hematopoietic stem cells (HSCs) when they start cycling to exit quiescence, which impairs blood production in FancA−/− mice." (PMID 35136057, 2022). "The known functions of these genes cluster into two main functional families, 3 out of 8 are DNA repair genes associated with Fanconi anemia: FANCD2, SLX4, and FANCA, while 3 out the 8 are HLA genes comprising the major histocompatibility complex (MHC) involving immunity." (PMID 35962345, 2022). "In addition, we identified two heterozygous truncating variants in members of the Fanconi anemia (FA) pathway, which were both transmitted by the respective fathers: p.(Lys998Glufs*60) in BRIP1 (Case-40, AML) and p.Arg880* in FANCA (Case-132, medulloblastoma)." (PMID 33840814, 2021). "Furthermore, we found that HSP90 inhibitors reduced the levels of Fanconi anemia factors such as FANCA, defining a plausible mechanism of how HSP90 inhibition compromises the repair of platinum-DNA adducts and thus sensitizes the cells towards cisplatin." (PMID 34944784, 2021). "The Fanconi anemia pathway comprises 19 gene products (FANCA to FANCT)." (PMID 33995067, 2021). "FANCA-associated Fanconi anemia has not yet been reported as differential diagnosis of SRS, but the clinical overlap is obvious." (PMID 33482836, 2021). "Interestingly, germline mutation rate of members of the Fanconi anaemia family of genes (including BRCA2, PALB2, BRIP1, RAD51C, FANCA, FANCI and FANCL) was 53.4% (31/58) among the patients with germline mutations in our cohort." (PMID 32091409, 2020).
Fanconi anemia (continued). "Indeed, it has been reported that following treatment with the DNA cross linking agent mitomycin C, phosphorylation of FANCA at S165 by AAK activates the Fanconi anemia/BRCA repair pathway." (PMID 32974133, 2020). "Interestingly, more than half of the possible pathogenic variants identified in patients with mesothelioma were located within genes of the Fanconi anemia pathway (FANCA, FANCC, FANCD2, and FANCM)." (PMID 31263571, 2019). "Additionally, Su-Dhl-4 cells treated with entinostat or tazemetostat also showed downregulation of RAD51, RAD54L, BRCA2, and three Fanconi anemia genes (FANCA, FANCB, and FANCM)." (PMID 31829282, 2019). "Interestingly, genes from the Fanconi Anemia pathway FANCA, FANCI, FANCD1 (also known as BRCA2) were enriched in radiosensitive GSCs compared to radioresistant GSCs." (PMID 30282933, 2018). "Though the family was nonsyndromic, we identified a combination of rare variants in Fanconi anemia (FA) genes FANCP/SLX4 (compound heterozygote - rs137976282/rs79842542) and FANCA (rs61753269) and a rare homozygous variant in the Holliday junction resolvase GEN1 (rs16981869)." (PMID 26201965, 2015). "More importantly, all six pathogenic FANCA mutant proteins we tested were defective in this interaction to different degrees, indicating that the interaction between FEN1 and FANCA physiologically contributes to the pathogenesis of Fanconi anemia." (PMID 24349332, 2013). "The FANCA gene is defective in more than 65% of Fanconi anaemia cases." (PMID 15860134, 2005). "Moreover, considering particular genes, deletions decreased their expression resulting in disease phenotypes, e.g., retinitis pigmentosa (deletion of an intron of the PRPF31 gene), DiGeorge syndrome (deletions within several genes), or Fanconi anaemia (deletion in exons of the FANCA gene)." (PMID 36564645, 2022). "While, unfortunately, none of the compounds tested were able to restore cellular FANCA-deficiency, our study shows the potential capacity to screen large compound libraries in the context of Fanconi anemia therapeutics in an optimized and cost-effective platform." (PMID 32605631, 2020). "Both in the 104-HIO and 106-HIO only minor gene expression differences could be detected between the presence and absence of the FANCA gene which could not be linked to the Fanconi anemia pathway directly." (PMID 32085439, 2020). "Although deficiency of each gene shows similar clinical and cellular phenotypes, ∼60% of Fanconi anemia patients presented defective FANCA, indicating that this protein may have additional biological functions beyond the canonical pathway through FANCI-FANCD2 monoubiquitination." (PMID 24170812, 2014). "For example, in the Fanconi Anemia pathway, RMI2 and FANCA demonstrated resistance patterns in 13 patients." (PMID 40294066, 2025). "Pathway analyses with the KEGG and REAC databases revealed a significant enrichment of the Fanconi anemia (FA) repair pathway, with notable genes such as BRIP1 (FANCJ), FANCI, FANCA, SLX4 (FANCP), UBE2T (FANCT), and C19orf40 (FAAP24)." (PMID 38896450, 2024). "The Fanconi anemia genes FANCB and FANCA exhibited recurrent amplifications and losses in 37 and 20% sarcoma cases, respectively." (PMID 36779660, 2023). "HRR alterations involve Fanconi anemia genes (PALB2, FANCA, FANCL, FANCI, FANCC), core RAD genes (RAD50, RAD51, RAD51B, RAD51C) as well as DNA damage response genes (ATM, ATR, CHEK1, CHEK2)." (PMID 36531003, 2022). "Deleterious alterations were also identified in nearly all (13/14) tumours in members of the Fanconi anaemia complementation groups, including FANCD2, FANCF, FANCC, FANCA, and FANCE." (PMID 34045664, 2022). "FANCA and FANCG (XRCC9) interact with each other and participate in the repair of interstrand crosslinks and DSBs via the Fanconi anemia pathway." (PMID 34573315, 2021).
Fanconi anemia (continued). "Fanconi anemia complementation group A (FANCA), one of Fanconi anemia complementation group (FANC) family genes, codes for a protein that is part of the Fanconi anemia (FA) complex." (PMID 33202820, 2020). "For the two Fanconi anemia (FA) patients (HIO-104 and 106, previously published as FA-A#1 IND-iPS1 and FA-A#2 IND-iPS3), FANCA expression was reconstituted as a prerequisite for generation of HIO via lentiviral expression of a doxycycline inducible construct." (PMID 32085439, 2020). "Suppression of FANCA and FANCD2 resulted in an increased frequency of radial chromosomal formation after treatment with mitomycin C as expected for these Fanconi anemia gene products." (PMID 28570559, 2017). "We also observed increased FANCA and FANCD2 (Fanconi Anemia complementation group A and D2) expression after IR; both genes being required for intra-S-phase checkpoint." (PMID 27495836, 2016). "Whereas, the binding of FANCC requires FANCA/FANCG binding and the products of other Fanconi Anemia genes." (PMID 25953249, 2015). "We efficiently generated iPSCs with homozygous mutations in KLF1, CDAN1 and FANCA genes without single-cell sorting and successfully applied the FANCA-edited cells for studying Fanconi anemia (FA) cellular phenotypes." (PMID 38081875, 2023). "Among these are polymerase (DNA directed), epsilon, catalytic subunit (POLE); PTEN; Fanconi anemia, complementation group A (FANCA); and CCR4-NOT transcription complex, subunit 3 (CNOT3) and others." (PMID 30143704, 2018). "Among DNA repair genes, we detected a high presence of members of the Fanconi Anemia Complementation Group (FANCC, FANCD2, FANCG, FANCA, and FANCE), which participate in homologous recombination DNA repair, and genes involved in double-strand break repair (BRCA2, BRIP1, BARD, BLM, CHEK2, and PALB2)." (PMID 30487452, 2018). "These genes include the Fanconi anemia pathway genes: FANCA, PALB2, BRIP1, RAD51C and XRCC2 and non-Fanconi anemia genes: ATM, CHEK2, NBN, RAD50, RAD51B, and RAD51D." (PMID 28202063, 2017). "Because MUS81-EME1 is also involved in resolution of Holliday junction, which is a later step in the Fanconi anemia pathway of ICL repair, we speculate that FANCA may additionally be involved in regulation of Holliday junction resolution catalyzed by MUS81-EME1." (PMID 24170812, 2014). "To this end, we took advantage of the Fanconi anemia patient cell line, GM6914, which does not express endogenous FANCA protein and GM6914 cells complemented with either empty vector (GM6914/EV) or HA-tagged wildtype FANCA (GM6914/FANCA)." (PMID 34360546, 2021).
breast carcinoma (45 papers, 2005 to 2025). "TWF1 has also been linked to breast cancer progression, while our study indicated that FANCA alterations negatively impacted TWF1 expression." (PMID 39844043, 2025). "FANCA mRNA is a potential biomarker for diagnosing breast cancer, and its overexpression is associated with the TNBC subtype, and its low expression is associated with low tumor grades." (PMID 39334297, 2024). "For instance, mutations in the FANCA gene can increase cellular activities including transcriptional basal efficiency or transcriptional regulation, increasing breast cancer risk." (PMID 35042833, 2022). "Heterozygous variants in genes of the FA pathway, including BRIP1 and FANCA, have been described to predispose to breast cancer." (PMID 33840814, 2021). "A significant association with the risk of breast cancer/breast and ovarian cancer was found for carriers of FANCA mutations (odds ratio (OR) = 3.14 95% confidence interval (CI) 1.4–6.17, p = 0.003)." (PMID 32235514, 2020). "The frequency of CCND1 amplification and FANCA loss was higher in TPBCs than in ER-PR-HER2+ breast cancers (CCND1: 26% vs. 6%, P = 0.013; FANCA, 72% vs. 50%, P = 0.023)." (PMID 31410192, 2019). "The genes that overlapped with the three other FST peaks were FANCA, a candidate for breast cancer susceptibility, PLAG1 that is associated with stature and body weight, and BIN1 that is associated with Alzheimer’s disease." (PMID 26089079, 2015). "Several studies have reported monoallelic germline mutation of FANCA in familial breast cancers, suggesting that FANCA may also be associated with breast cancer susceptibility." (PMID 34058059, 2022). "Reduced levels of FANCA and FANCD2 in AML and breast cancer, respectively, have also been reported, although the causes of these reduced FANCA and FANCD2 levels remain unknown." (PMID 34884777, 2021). "Since FANCA mutations are highly common in gynecological malignant tumors such as breast cancer, further studies including DEB and MMC stress test to determine the factors that render leiomyoma benign and biomarkers that predict the growth patterns of leiomyoma will be of great benefit." (PMID 33202820, 2020). "FANCA variants have been reported in non-BRCA1/2 familial breast cancer patients." (PMID 30709382, 2019). "In addition, SNPs in FANCA are associated with an 8% increase in breast cancer risk." (PMID 33585230, 2020). "Mutations in the FANCA gene have been proven to be linked to a higher possibility of carrying BRCA1/2 mutations and less response to DNA damage, which increase the risk of breast cancer." (PMID 39334297, 2024). "For example, the FANCA and FANCI genes which have been implicated in breast cancer, had pathogenic variants detected in both breast cancer patients and individuals with hereditary breast and ovarian cancer (HBOC)." (PMID 37461096, 2023). "FA is caused by the failure of the Fanconi anemia/breast cancer (FA/BRCA) pathway; thus far, 22 genes (FANCA to FANCW) that participate in this pathway have been identified." (PMID 33371494, 2020). "A similar high rate of occurrence in normal populations was observed for FANCA p.S1088F (9/97 in breast cancer cases vs 11/94 in controls)." (PMID 26485759, 2015). "Among the patients included in our study, five presented a family history of breast cancer in first-degree relatives, but only one case presented FANCA and BRCA1 alterations." (PMID 23483937, 2013). "Additionally, we discovered trans correlations between specific gene alterations (FANCA, HRAS, PIK3CA, MAP2K1, JAK2) and the expression of 22 proteins, suggesting potential molecular mechanisms underlying breast cancer development and progression." (PMID 39844043, 2025). "Notably, each of these variants is unique to a single patient, and 2 patients were carriers for two variants each: Patient H3168 had stop gain variants in FANCA and PALB2, and had a sister with lung cancer, and another sister with breast cancer." (PMID 37461096, 2023).
breast carcinoma (continued). "FANCA variants are a significant risk factor for breast cancer among the population without BRCA1/2 loss." (PMID 31931827, 2020). "FANCA has been shown to be upregulated in response to various chemotherapeutic treatments in ovarian cancer spheroids, and knockdown has resensitized resistant breast cancer cell lines to cisplatin." (PMID 36046263, 2020). "FANCA K1283R appeared three times in breast cancer out of seven cases." (PMID 30709382, 2019). "However, the role of the FA genes most commonly mutated, FANCA and FANCC, in the risk of developing breast cancer has remained uncertain." (PMID 31467304, 2019). "However, they describe two cases who have PVs in moderate to low breast cancer risk genes (ATM/PALB2; case 119, ATM/FANCA; case 122) with bilateral breast cancer at age 35 and breast cancer at age 35 respectively – highlighting multiple and young onset cancers." (PMID 39843919, 2025). "Notably, the observed synthetic lethality between PARPi and FANCA deficiency was not restricted to breast cancer models." (PMID 40630542, 2025). "A study analyzed FANCA gene in breast cancer patients and found multiple alternative splicing events, including the insertion of intronic portion and exon skipping, suggesting the alternative splicing events of FANCA may play critical function in biology." (PMID 37168687, 2023). "Furthermore, R-loops accumulate in human cells depleted of DNA repair factors that act during replication, such as those involved in the FA/BRCA pathway, that is in the tumor suppressor and breast cancer-susceptibility genes BRCA1 and BRCA2 or the Fanconi anemia (FA) factors FANCD2, FANCA or FANCM." (PMID 28653981, 2017). "PRMT5 expression was moderately to strongly correlated (Pearson score ≥ 0.4) with established DDR genes such as BRCA1, BRCA2, RAD51, RAD51D, RAD51AP1, FANCA, and FANCI across 125 ovarian and breast cancer cell lines." (PMID 37861290, 2023). "In this study, however, FANCA did not rank as a prognostic factor in breast cancer which strengthens the importance of FAAP20’s repair roles in cancer cells." (PMID 37620397, 2023). "We studied CBFA2T3, FANCA, FBXL8, LRRC29, TERF2 and TERF2IP, six potential breast cancer TSG candidate genes located on the long arm of chromosome 16, which is involved in LOH in more than 50% of breast cancer cases." (PMID 16280054, 2005). "A previous study of familial breast cancer cases did not identify mutations in FANCA, C, D2, E, F, G, so at present it remains unclear whether FANCC, which acts upstream of FANCD2, is a breast cancer predisposing gene." (PMID 18786261, 2008).